ENSG00000287839 (novel protein)
Gene: Protein-coding gene on chromosome 1 (155,626,755 to 155,648,640, reverse strand). Ensembl gene ENSG00000287839.
Gene Ontology:
Molecular function: DNA-directed DNA polymerase activity; endonuclease activity; hydrolase activity; nuclease activity; nucleic acid binding; nucleotidyltransferase activity; RNA-directed DNA polymerase activity; RNA-DNA hybrid ribonuclease activity; structural molecule activity; transferase activity; zinc ion binding
Biological process: DNA integration; DNA recombination; DNA transposition; DNA-templated DNA replication; RNA-templated DNA biosynthetic process
Cellular component: chromosome